FCGR3A (Fc gamma receptor IIIa)
Diseases named in the same sentence as FCGR3A in open-access papers (continued):
Sharing a sentence is not in itself a finding about the gene and the disease.
tumor (continued). "mRNA of the FCGR3A gene was detected in all tumor tissue samples under study; in contrast, mRNA of the FCGR3B gene was found only in 92.0% (115/125) of cases." (PMID 37064811, 2022). "TCGA clinical data analysis found that the expression of FCGR3A had a unique correlation with the clinicopathological features of PCa, which was closely related to the tumor stage." (PMID 36505767, 2022). "In tumors classified as pT1, the mRNA content of the FCGR3A gene was significantly lower than that in tumor samples of pT3 size." (PMID 37064811, 2022). "TMA and TCGA results showed that FCGR3A was highly expressed in tumor T2 stage (which was consistent with the result of tissue microarray), but showed the opposite result in tumor T3 stage." (PMID 36505767, 2022). "Through GO/KEGG and GESA, we found that FCGR3A was involved in many pathologic and physiological processes, and was most closely related to tumor immune-related pathways." (PMID 35668930, 2022). "We also examined the differential expression of FCGR3A in patients with different tumor types based on the main pathological stage and found that FCGR3A expression was only related to tumor stage in 5 cancers, including ACC, ESCA, KICH, SKCM, and STAD." (PMID 35668930, 2022). "The presence of a tumor thrombus in the inferior vena cava system was accompanied by a significant increase in the mRNA content of the FCGR3A gene." (PMID 37064811, 2022). "The PD-L1 inhibitor avelumab was used which represents an antibody with preserved effector functions that have been previously shown to induce direct tumor cell killing, especially in subjects expressing the FCGR3A high-affinity SNP rs396991." (PMID 35936668, 2022). "The results showed that the mRNA levels of FCGR1A/B/C and FCGR3A were correlated with the tumor stages of ccRCC patients, whereas the mRNA levels of FCGR2A/B/C and FCGR3B did not markedly differ among tumor stages." (PMID 35372055, 2022). "Evaluating data from a cohort of patients treated with high doses of IL-2, it was found that when the higher-affinity genotypes for FCGR2A, FCGR3A, and FCGR2C were considered together, they were associated with increased tumor shrinkage and prolonged survival." (PMID 32013092, 2020). "Additionally, TNMplot database analysis revealed that tumor tissues had greater levels of FCGR3A and RNASE2 mRNA expression than healthy tissues." (PMID 39574475, 2024). "Additionally, FCGR3A+NK cells were enriched in tumor samples, indicating that tumor-infiltrating NK cells primarily originated from peripheral blood." (PMID 38311726, 2024). "Moreover, it was determined by the EdU and CCK-8 assays that inhibiting FCGR3A markedly decreased the ability of tumor cells in the pancreas to proliferate." (PMID 39574475, 2024). "TIMER was used to analyze the correlations among FCGR3A and tumor-infiltrating immune cells." (PMID 39280892, 2022). "Due to the high expression of FCGR3A, these cells may be recruited from peripheral blood, suggesting that peripheral NKs are the main source of tumor-infiltrating NKs." (PMID 35812401, 2022). "Therefore, the activities of cDC-CD1C-AREG, macrophage-IL1B and Mono-FCGR3A in low tumor infiltration group were elevated as innate immune cells and APCs, but suppressed in high tumor infiltration group." (PMID 36532059, 2022). "In order to observe the expression and enrichment status of FCGR3A in GO pathway sets, we divided the human tumor samples into high expression and low expression group according to the median FCGR3A expression and analyzed the enrichment of the GO signaling pathway in the two groups by GSEA." (PMID 35668930, 2022). "According to our results, the expression of FCGR3A was positively correlated with the expression of MMRs genes in most tumors, suggesting that FCGR3A may maintain the viability of tumor cells by up-regulating DNA mis-match repair-related genes." (PMID 35668930, 2022). "We observed the genetic alteration status of FCGR3A in different tumor samples of the TCGA cohorts." (PMID 39280892, 2022).
tumor (continued). "The significance of our work is to prospectively reveal the interaction of FCGR3A in the tumor microenvironment and provide insights based on bioinformatics and computational biology for further understanding the role of FCGR3A in tumor metabolism and immune regulation." (PMID 35668930, 2022). "However, Mono-FCGR3A in high tumor infiltration group expressed lower levels of MHC molecules, inflammatory cytokines and chemokines (HLA-DRB1/HLA-DPB1, TNF, IL1B, CCL3 and CCL4), which meant the sub-cluster was less involved in immune responses." (PMID 36532059, 2022). "However, the expression and prognosis value of FCGR3A and correlation with tumor-immune infiltrate in LGG remain unclear." (PMID 39280892, 2022). "Similarly, our study reached the same conclusion, suggesting that FCGR3A may influence DNA methylation and promote tumor development, although the detailed mechanism is still unknown." (PMID 35668930, 2022). "However, a possible mechanism is that the high-affinity allele V of V158F within FCGR3A might contribute to decreased ADCC-triggered by NK cell, but through cross-linking of the FCGR to increase activation of TAM in tumor microenvironment by anti-EGFR mAb." (PMID 26363448, 2015). "Moreover, polymorphisms in the genes coding for the receptors mainly responsible for ADCC, i.e., Fc fragment of IgG, low affinity IIa, receptor (FCGR2A, also known as CD32) and FCGR3A (also known as CD16a), have been shown to influence the response of cancer patients to most tumor-targeting mAbs." (PMID 25537519, 2014). "FCGR3A suggested active ADCC in NK cells, while high B2M expression enhanced tumor immunogenicity, helping suppress cancer." (PMID 40104502, 2025). "Gene co-expression network analysis suggested that FCGR3A, FGL2, and their co-expressed genes were involved in inflammatory activities and tumor-related signaling pathways." (PMID 39629005, 2024). "While the HAS group was enriched in tumor cells and showed a lower infiltration of CD8-CCR7, CD8- CXCL13, CD8-GNLY, FCGR3A NK cells, XCL1 NK cells, plasma cell (PC) and other immune subsets." (PMID 39267750, 2024). "CD8-05-FGFBP2 cluster exhibited a CD8+ effector phenotype, upregulating genes involved in cytotoxicity and anti-tumor activity: FGFBP2, GNLY, FCGR3A, GZMH, PRF1, TGFBR3, and GZMB." (PMID 36350695, 2022). "The main cell clusters included T cells (CD3E and CD3D), B cells (CD19), natural killer cells (NCAM1, FCGR3A and KLRD1), myeloid cells (CD86 and CD163) and tumor cells (EPCAM, KRT8 and KRT18)." (PMID 36497182, 2022). "Subclustering of natural killer (NK) cells revealed well-known NCAM1- and FCGR3A- expressing subsets and an interesting keratin (KRT81 and KRT86)-expressing subset potentially enriched in tumor tissues." (PMID 36423636, 2022). "CX3CR1 and CSF1R are highly expressed in FCGR3A+ (CD16+) subset, which can be identified as an inflammatory phenotype in anti-tumor immune response." (PMID 33648605, 2021). "While typical macrophage markers such as CD68, FCGR3A, MARCO, and CD14 were highly expressed in TAMs as well as non-tumor macrophage samples, the expression of canonical M1, M2, and TAM markers was more diverse." (PMID 33918618, 2021). "Expression of membrane receptors such as FCGR3A and CX3CR1, and cytotoxic genes like GZMB, FGFBP2, PRF1, and GNLY increased gradually during this transition, implying a gradually acquired tumor-killing ability in CD56dim NK cells." (PMID 33298893, 2020). "In the case of FCGR3A, if only (FFPE) tumour tissue is available, the best methodology is one that is sensitive to the presence of both alleles, even if one is present at low frequency due to LOH." (PMID 23286345, 2013). "Based on these data, we can speculate that cells co expressed with FCGR3A and FGL2 migrate from peripheral blood into the tumor." (PMID 39629005, 2024).
tumor (continued). "In addition, C2 overexpressed the dimNK-related marker FCGR3A, while C1 overexpressed the briNK-related marker XCL1 which has been shown to recruit conventional type 1 DCs to the tumour microenvironment." (PMID 36855107, 2023). "Normal skin and testis tissues showed not detected staining with FCGR3A IHC, while tumor tissues showed medium staining." (PMID 35668930, 2022). "Non-tumor components included endothelial cells (expressing VWF, CDH5, ECSCR, SLCO2A1, and MYCT1), pericytes (marked by RGS5, MCAM, and PDGFRB), normal oligodendrocytes (showing PTGDS, MBP, TF, and MOG expression), and TAMs (identified by CD14, AIF1, FCER1G, FCGR3A, TYROBP, and CSF1R)." (PMID 41394801, 2025). "The major finding was that except for FCGR3A, for which there was no significant variation of the expression levels between the different groups, non-metastatic SLNs had a different profile from NLNs, confirming the immune recognition of the primary tumour." (PMID 39199652, 2024). "Therefore, the upregulation of FCGR3A and FGL2 expression is induced by the tumor." (PMID 39629005, 2024). "Here, we first analyzed the relationship between FCGR3A expression and the infiltration levels of six common immune cells (B cells, CD4+T cells, CD8+T cells, DC cells, macrophages, and neutrophils), and observed a positive correlation in the vast majority of tumor types." (PMID 35668930, 2022). "Moreover, compared with the normal kidney tissues, the stromal populations (from FCGR3A to CSF1R) were notably increased, indicating that stromal populations may regulate tumor progression." (PMID 28846080, 2017). "Furthermore, to identify tumor cell types that predominantly express FCGR3A, we analyzed FCGR3A gene expression levels in pan-cancer single cell lines using the GDSC database and the CancerSCEM website, and the results showed that FCGR3A was highly expressed in most tumor cell lines." (PMID 35668930, 2022). "The third subset consists of FCGR3A + non-classical monocytes that exhibit expression of genes stimulated by interferon, akin to the"IFN-responsive"cells identified in murine tumor models." (PMID 41035074, 2025). "On the basis of the principle of ceRNA hypothesis, C22orf34, RFPL1S, and LINC00996 shared same expression patterns as CXCL10, CXCL9, CCL5, FCGR3A, and CCR2, all which were upregulated in tumor tissues of PTC with HT compared with those without HT." (PMID 36266640, 2022).
cancer (107 papers, 2007 to 2026). A tumor composed of atypical neoplastic, often pleomorphic cells that invade other tissues. "Xu confirmed that FCGR3A had highly significant positive associations with FCGR1A in various cancers." (PMID 40660309, 2025). "We further used the CGGA-LGG database to compare the difference in FCGR3A mRNA expression in groups divided by age, gender, cancer type, WHO grade, 1p19q codel, IDH1-mutation, MGMT methylated, radiotherapy treatment, and chemotherapy treatment." (PMID 39280892, 2022). "High FCGR3A expression was mainly associated with poor prognoses of six cancer types (KIRC, LGG, THYM, PRAD, and UVM), while it was associated with good prognoses of SKCM and THCA." (PMID 35668930, 2022). "Our findings also confirmed that FCGR3A had highly significant positive associations with FCGR1A in four cancers." (PMID 33344503, 2020). "The present study revealed that FCGR3A is involved in constructing the risk score cancer model, and effectively predicts patient prognosis, correlating with lower infiltration of B cells naive and CD8+ T cells, and higher infiltration of M2 Macrophages and Neutrophils." (PMID 39574475, 2024). "Survival analysis revealed that FCGR3A predominated as a risk prognostic factor in most cancers." (PMID 35668930, 2022). "Fc fragment of IgG receptor IIIa (FCGR3A) gene polymorphism may correlate with some cancers' treatment responses." (PMID 39280892, 2022). "Extensive data points toward the fact that patients with higher-affinity FCGR2A-p.166His or FCGR3A-p.176Val alleles have an enhanced response to monoclonal antibody-mediated anti-cancer therapy amongst solid tumors of the breast, head and neck, colorectal carcinomas as well as lymphomas." (PMID 31632391, 2019). "For example, many studies investigating associations with therapeutic efficacy of therapeutic antibodies against cancer have found an association with the FCGR3A-158V variant (rs396991), which we now show to be in moderate LD with the classic FCGR2C-ORF (r2 = 0.24)." (PMID 30949161, 2019). "IRF8, RTEL1, and FCGR3A mutations are associated with NKD but their associations with cancer are unknown." (PMID 31379882, 2019). "IRF8, RTEL1, and FCGR3A mutations have been observed in NKD patients but their association with cancer is unknown." (PMID 31379882, 2019). "According to survival analysis, FCGR3A predominates in most cancers and serves as a prognostic factor." (PMID 39574475, 2024). "FCGR3A mRNA expression levels were analyzed by using different databases to detect FCGR3A expression across a wide range of cancers." (PMID 35668930, 2022). "We found that FCGR3A was overexpressed in 23 cancers, and IHC analysis confirmed this trend at the protein level." (PMID 35668930, 2022). "The role of FCGR3A in cancer needs to be further explored and verified through biological experiments in the future." (PMID 35668930, 2022). "We performed the first comprehensive bioinformatics analysis of FCGR3A expression and prognostic value in human cancers." (PMID 39280892, 2022). "We investigated the impact of FCGR3A expression on survival rates in different cancers using the GEPIA and OncoLnc databases." (PMID 39280892, 2022). "In this study, we first analyzed the mRNA expression of FCGR3A in different cancers and then focused on LGG." (PMID 39280892, 2022). "FCGR3A expression showed significant positive correlation with almost all immunosuppressive genes and chemokine genes in pan-cancer." (PMID 35668930, 2022). "Gene co-expression analysis was performed to explore the relationship between FCGR3A and the expression levels of immunosuppressive genes and chemokines in 33 TCGA-cancers." (PMID 35668930, 2022). "SNPs in FCGR2A and FCGR3A genes influencing mAb affinity for FcγR have previously been shown to modify antibody immunotherapy in cancer patients." (PMID 30899264, 2019).
cancer (continued). "Recently, researchers have found that FCGR3A is highly expressed in pan-cancer, including PCa, and it could be an independent biomarker for PCa patients." (PMID 37494663, 2023). "In addition, FCGR3A expression was associated with CD8+ T cell levels in 25 cancer types, CD4+T cell levels in 28 cancer types, macrophage levels in 27 cancer types, neutrophil levels in 30 cancer types, and dendritic cell (DC) levels in 30 cancer types." (PMID 39280892, 2022). "Likewise, cancer grades analysis by TISIDB indicated that mRNA expressions of FCGR1A/B, FCGR2A/B/C, and FCGR3A correlated with cancer grade of ccRCC." (PMID 35372055, 2022). "Therefore, we comprehensively examined FCGR3A in pan-cancer based on data from TCGA and GTEx databases." (PMID 35668930, 2022). "Therefore, we investigated the correlation of FCGR3A expression with immune infiltration levels in 32 cancer types from the TIMER database." (PMID 39280892, 2022). "While many studies have reported associations between the high affinity FCGR2A and FCGR3A alleles and greater mAb efficacy in numerous cancers, others have not observed such associations, perhaps due to differing and complex biological backgrounds." (PMID 30899264, 2019). "The six upregulated genes (FCGR3A, LPAR5, MATK, MNDA, TMEM144, and CD84) play key immunomodulatory roles in cancer progression and metastasis." (PMID 40340807, 2025). "The immunohistochemical analysis revealed significantly higher expression of CD44, MYC, IL17A, CXCL1, FCGR3A, SPP1, and IL1A in cancer tissues, while CXCL12 and CCL5 showed significantly higher expression in adjacent normal tissues." (PMID 39767563, 2024). "CD8A, FCGR3A, and PTPRC are identified as candidate biomarkers in various cancers or important molecules in PCa patients with bone metastases." (PMID 37494663, 2023). "To evaluate the effect of FCGR3A expression on prognosis, we conducted univariate Cox regression analysis to analyze the relationship between FCGR3A expression and OS, DSS and PFS in TCGA pan-cancer." (PMID 35668930, 2022). "The relationship between FCGR3A and FCGR1A displayed highly significant positive correlation in four cancers." (PMID 33344503, 2020). "Through a study of the HPA repository, it was possible to determine that cancerous pancreatic tissues had higher levels of FCGR3A protein expression than normal tissues executed, but there was not a significant distinction in RNASE2 protein expression between cancer and healthy tissues." (PMID 39574475, 2024). "In various cancer types, NK cells are typically categorized into two main subsets, including CD56bright CD16low and CD56dim CD16high, which are characterized by their distinctive expression patterns of the canonical cell markers NCAM1 and FCGR3A." (PMID 39033089, 2024). "Therefore, FCGR3A and HAVCR2 are highly expressed in various cancer models and are likely to participate in the immune process of NK cells." (PMID 36505767, 2022). "We used the GEPIA database to study differences in FCGR3A expression across 33 TCGA cancer types and TCGA and GTEx normal tissues." (PMID 39280892, 2022). "Also, FCGR1A is involved in many pathophysiological processes and is closely related to FCGR3A, SYK, and HCK in various cancers." (PMID 33344503, 2020). "The cancers have been observed in NKD patients with GATA2 and MCM4 mutations although not in patients with IRF8, RTEL1, and FCGR3A mutations." (PMID 31379882, 2019). "One of these targets FCGR3A (CD16a) for NK cell redirection, while the other 26 bispecific antibodies target CD3E on T cells to redirect the cytotoxic T cells (CTLs) to kill and lyse cancer cells." (PMID 28822103, 2018). "Additionally, CNV analysis identified amplification of PNP, FCGR3A, and CFHR1 as well as deep deletion of ETV6, CFHR1, and RPS15 as the most frequently detected copy number altered PID-related genes across the four available pediatric cancer cohorts." (PMID 36497424, 2022).